IQGAP1 (IQ motif containing GTPase activating protein 1)
Description:
Plays a crucial role in regulating the dynamics and assembly of the actin cytoskeleton. Recruited to the cell cortex by interaction with ILK which allows it to cooperate with its effector DIAPH1 to locally stabilize microtubules and allow stable insertion of caveolae into the plasma membrane (By similarity). Binds to activated CDC42 but does not stimulate its GTPase activity. Associates with calmodulin. May promote neurite outgrowth. May play a possible role in cell cycle regulation by contributing to cell cycle progression after DNA replication arrest.
Synonyms: KIAA0051; p195; SAR1; HUMORFA01
Tractability: Small molecule: it has a high-quality binding pocket. Antibody: UniProt places it where antibodies can reach, with high confidence; its Gene Ontology location is reachable by antibodies, with high confidence; the Human Protein Atlas places it where antibodies can reach. PROTAC: ubiquitination databases record sites on it; its protein half-life has been measured.
Gene: Protein-coding gene on chromosome 15 (90,388,207 to 90,502,239, forward strand). Ensembl gene ENSG00000140575.
Subcellular location: Cell membrane; Nucleus; Cytoplasm; Cytoplasm, cell cortex; Apical cell membrane; Basolateral cell membrane
Subcellular location (Human Protein Atlas): Cell Junctions; Plasma membrane
Pathways (Reactome):
Signal Transduction: CDC42 GTPase cycle; MAP2K and MAPK activation; RAC1 GTPase cycle; RAC2 GTPase cycle; RHO GTPases activate IQGAPs; RHOA GTPase cycle; RHOC GTPase cycle; RHOQ GTPase cycle; RHOU GTPase cycle; RHOV GTPase cycle
Disease: Paradoxical activation of RAF signaling by kinase inactive BRAF; Signaling by BRAF and RAF1 fusions; Signaling by RAF1 mutants; Signaling by high-kinase activity BRAF mutants; Signaling by moderate kinase activity BRAF mutants; Signaling downstream of RAS mutants
Cell-Cell communication: Nephrin family interactions
Immune System: Neutrophil degranulation
Metabolism: Glucagon-like Peptide-1 (GLP1) regulates insulin secretion
Gene Ontology:
Molecular function: cadherin binding; calcium ion binding; calmodulin binding; MAP-kinase scaffold activity; molecular adaptor activity; phosphatidylinositol-3,4,5-trisphosphate binding; protein binding; protein domain specific binding; protein kinase binding; protein phosphatase binding; protein serine/threonine kinase activator activity; S100 protein binding; small GTPase binding; actin filament binding; GTPase activator activity; GTPase inhibitor activity
Biological process: cell migration; cellular response to calcium ion; cellular response to epidermal growth factor stimulus; epidermal growth factor receptor signaling pathway; positive regulation of MAPK cascade; regulation of actin cytoskeleton organization; regulation of mitotic cell cycle; fibroblast migration; mitotic actomyosin contractile ring assembly actin filament organization; podocyte development; signal transduction; caveola assembly; cellular response to fibroblast growth factor stimulus; cellular response to platelet-derived growth factor stimulus; fibroblast growth factor receptor signaling pathway; MAPK cascade; platelet-derived growth factor receptor signaling pathway
Cellular component: apical plasma membrane; cell junction; cytoplasm; cytoplasmic ribonucleoprotein granule; cytoplasmic side of plasma membrane; extracellular exosome; focal adhesion; microtubule; midbody; nucleus; plasma membrane; ruffle; actin cytoskeleton; actin filament; basolateral plasma membrane; cell cortex; cytosol; neuron projection; secretory granule membrane; slit diaphragm; cell leading edge; cell-cell junction; cortical actin cytoskeleton; lateral plasma membrane; plasma membrane bounded cell projection; and 1 more
Genetic constraint (gnomAD): Loss-of-function variants: 50 observed, 160.25 expected, observed/expected ratio (o/e) 0.31, 90% interval 0.25 to 0.4. The upper end of that interval is the gene's LOEUF score, 0.4, which puts it in group 1 of 6, group 1 being the genes least tolerant of losing a copy. Missense variants: 1,430 observed, 1,680.1 expected, observed/expected ratio (o/e) 0.85, 90% interval 0.81 to 0.89. Synonymous variants: 642 observed, 629.43 expected, observed/expected ratio (o/e) 1.02, 90% interval 0.95 to 1.09.
Homologues: Orthologues: chimpanzee IQGAP1 (99% identical), macaque IQGAP1 (98% identical), rabbit IQGAP1 (97% identical), pig IQGAP1 (96% identical), mouse Iqgap1 (96% identical), rat Iqgap1 (95% identical), guinea pig IQGAP1 (93% identical), tropical clawed frog iqgap1 (83% identical), zebrafish iqgap1 (77% identical), dog IQGAP1 (69% identical), Caenorhabditis elegans pes-7 (24% identical). Paralogues in human: IQGAP2 (59% identical), IQGAP3 (58% identical).
Diseases named in the same sentence as IQGAP1 in open-access papers:
IQGAP1 is named in the same sentence as 136 diseases in open-access papers, as found by Europe PMC text mining. Sharing a sentence is not in itself a finding about the gene and the disease. The quoted sentences say what the papers report.
breast carcinoma (36 papers, 2012 to 2025). "Meanwhile, the polarization of Clip170 tension induced by the subcellular distribution of IQGAP1 is closely associated with the directionality of breast cancer migration." (PMID 36209218, 2022). "We establish that the molecular scaffolds β-arrestins and IQGAP1 associate with each other in breast cancer cells, to perhaps fine tune their signaling capacity." (PMID 23405264, 2013). "Clinically, these pathways could represent actionable vulnerabilities; targeting IQGAP1 or its interaction networks might offer novel therapeutic strategies for PALB2-mutated breast cancers, particularly those resistant to conventional DNA repair-targeted treatments." (PMID 40868059, 2025). "In breast cancer, IQGAP1 directly interacts with HER2, regulating its phosphorylation and stability." (PMID 41035668, 2025). "An in vivo study found that IQGAP1 expression is significantly elevated in breast cancer cells compared to normal breast cells." (PMID 41035668, 2025). "Another Rho family member, Cdc42, was found to interact with IQGAP1, directly affecting actin cytoskeleton dynamics and filopodia formation, thereby promoting breast cancer cell metastasis." (PMID 41035668, 2025). "These pleiotropic effects point to the potential of IQGAP1 as both a biomarker and a therapeutic target in PALB2-mutated breast cancers." (PMID 40868059, 2025). "EGFR: The EGFR:IQGAP1 complex was identified by mass spectrometry, and later confirmed in A431 epidermoid carcinoma, breast carcinoma, and ovarian cancer cells." (PMID 37071417, 2023). "IQGAP1 has been shown to be an oncogene, where overexpression of IQGAP1 in vitro increases invasion and motility in breast cancer cells (MCF-7 and MDA-MB-231)." (PMID 36499281, 2022). "IQGAP1 can also promote breast cancer cell proliferation and migration through the RAS-MAPK pathway and CDC42/RAC1 pathways." (PMID 34439095, 2021). "More experiments are necessary to prove the significance of IQGAP1-IQGAP2 interaction with regards to breast cancer progression." (PMID 33846302, 2021). "Next, we will summarize the current evidence on contributions of IQGAP1 to different types of carcinoma, with a particular emphasis on head and neck cancer, but also including carcinomas of breast, pancreas, liver, colon, gastric, lung, and ovary." (PMID 34439095, 2021). "Suppression of IQGAP1-mediated ERK activation is a possible route via which IQGAP2 restricts oncogenic properties of breast cancer cells." (PMID 33846302, 2021). "Intriguingly, pro-tumorigenic roles of IQGAP1 were observed in breast cancer; its cytosolic and nuclear expressions, where IQGAP1 was co-localized with BRCA1, were detected in triple negative breast cancer." (PMID 33498739, 2021). "Next, we examined the correlation between IQGAP2/phospho-ERK and IQGAP1/phospho-ERK in breast cancer tissues." (PMID 33846302, 2021). "MicroRNAs (miRNAs), important regulators of a wide range of cellular processes, also impact breast cancer development through IQGAP1." (PMID 34439095, 2021). "The ratio of IQGAP2/IQGAP1 would be crucial in assigning the prognostic significance for breast cancer." (PMID 33846302, 2021). "Knocking down IQGAP1 inhibits growth of HER2-positive breast cancer cells and increases their response to trastuzumab, an antibody-based drug that inhibits the activity of the HER2 receptor." (PMID 34439095, 2021). "We carried out this study with the primary aim to establish the role and molecular mechanism of IQGAP2 in breast cancer progression and its relation with IQGAP1." (PMID 33846302, 2021). "IQGAP1 can bind directly to the estrogen receptor (ER), a major contributor to breast cancer progression, and promote estrogen-dependent transcription and cell proliferation." (PMID 34439095, 2021). "In this study, we therefore present clear evidence that IQGAP1 is critical for metastasis in vivo, both in melanoma and breast cancer models." (PMID 32051509, 2020).
breast carcinoma (continued). "In this study, we use both knockdown and knockout of IQGAP1 to investigate its role in the metastatic cascade of both melanoma and breast cancer cells in vivo." (PMID 32051509, 2020). "IQGAP1 knockout thus reduced metastasis in vivo in both melanoma and breast cancer cell lines, indicating a more generally conserved role for IQGAP1 in the metastatic cascade." (PMID 32051509, 2020). "Meanwhile, the scaffold protein IQGAP1 and procathepsin D can also interact with Cdc42 to enhance breast cancer cell growth and invasion in a MEK/ERK-dependent manner." (PMID 30754684, 2019). "In particular, they reported that, in IQGAP1-silenced breast cancer cells, trastuzumab increased its capacity to decrease HER2 expression and HER2-stimulated activation of the PI3K/AKT cascade." (PMID 26919099, 2016). "The overexpression of IQGAP1 in colon cancer cell correlates with poor prognosis, and cell motility was increased by overexpressing IQGAP1 in breast cancer." (PMID 26252773, 2015). "Multiple studies have shown that IQGAP1 is up-regulated in many human malignancies, such as lung cancer, ovarian cancer, colon cancer, breast cancer, melanoma and HCC." (PMID 26252773, 2015). "Rap1A has been shown to interact directly with the actin-binding protein, IQGAP1, which has established roles in breast cancer cell migration and invasion." (PMID 23405264, 2013). "Although it is not surprising that knock-down of IQGAP1 disrupted general cell invasion, we found that LPA-induced breast cancer cell invasion specifically required the presence of IQGAP1, thus establishing it as a key player in this process." (PMID 23405264, 2013). "WAVE2 also forms a complex with IQGAP1 and kinesin-1 in growth-arrested breast cancer cells, and the amounts of these proteins relative to WAVE2 increase after stimulation of the cells with growth factor." (PMID 22315597, 2012). "Recently, Sayedyahossein et al48 reported identification of small molecules that disrupt binding of Cdc42 and IQGAP1 and inhibit proliferation and migration of breast carcinoma cells lending further credence to the approach of targeting the GRD domain of IQGAP1." (PMID 38834690, 2024). "Our findings not only provide critical insights into the role of Hax1 on migration of the epithelial cell layer in breast cancer cell lines, but also unravel a novel interaction between IQGAP1 and Hax1 and demonstrate its relevance in FA dynamics and cell migration." (PMID 37488602, 2023). "Loss of IQGAP1 impairs LPA-stimulated invasion and migration of breast carcinoma cells." (PMID 37071417, 2023). "More research is underway to determine whether the IQGAP1-SigmaR1 axis is a direct target of Haldol in breast cancer as well as brain cancer." (PMID 37444574, 2023). "Because GPR161 and IQGAP1 are both overexpressed in breast cancer, their crosstalk may participate in carcinogenesis." (PMID 37071417, 2023). "Analysis was performed in both MCF7 breast carcinoma cells with stable knockdown of IQGAP1 by siRNA (termed MCF7-siIQ8) and control MCF7 cells, to decipher whether the cytotoxicity could be caused by the disruption of the target protein–protein-interaction." (PMID 36253497, 2022). "Filopodia and lamellipodia formation are considered as highly aggressive phenotypes in breast cancer, and whether IQGAP1 and IQGAP2 are correlated with the formation of filopodia and lamellipodia was unclear." (PMID 36209218, 2022). "Our findings with GST-Pull-down experiments show the presence of an IQGAP2-IQGAP1 complex in breast cancer cells, hinting at the possibility of masking the pro-oncogenic effects of IQGAP1 and subsequent reduction of the phospho-ERK levels in the cells, similar to the phenomenon observed in HCC21." (PMID 33846302, 2021). "IQGAP1 was first discovered to promote tumorigenesis in breast cancer." (PMID 34439095, 2021). "IQGAP1-mediated PI3K signaling is also critical for breast cancer survival." (PMID 34439095, 2021).
breast carcinoma (continued). "Subsequent studies demonstrated that IQGAP1 contributes to breast cancer through multiple pathways." (PMID 34439095, 2021). "Furthermore, IQGAP1 knockout reduced spontaneous metastasis of LM2 breast cancer cells from primary tumors to both the lungs and liver by a similar or even greater degree, even when normalizing for any changes in primary tumor mass." (PMID 32051509, 2020). "We investigated the effects of IQGAP1 knockdown and knockout on both experimental and spontaneous metastasis models in vivo, and we found that reduction in IQGAP1 levels curtailed the formation of metastases from both melanoma and breast cancer cells." (PMID 32051509, 2020). "Moreover, IQGAP1 protein level was found to be negatively correlated with the response to CY-9d in both ER/PR-positive breast cancer cells and TNBC cells." (PMID 29262632, 2017). "Thus our data establish novel roles for Rap1A and IQGAP1 as critical regulators of LPA-induced breast cancer cell migration and invasion." (PMID 23405264, 2013). "Depletion of IQGAP1 blocked LPA-stimulated breast cancer cell invasion." (PMID 23405264, 2013). "Finally, IQGAP1 also contributes to resistance in targeted therapies for breast cancer." (PMID 41035668, 2025). "However, previous results in the MCF-7 breast cancer cell line showed that altering IQGAP1 expression could affect primary tumor growth." (PMID 32051509, 2020). "Although it has been demonstrated that IQGAP1 directly interacts with Rap1A in vitro, using purified proteins, whether or not this association occurs in breast cancer cells is not known." (PMID 23405264, 2013). "IQGAP1 knockdown alters HER2 stability, activation, and signaling to Akt, which reduces breast cancer cell proliferation." (PMID 37071417, 2023). "Previous studies have demonstrated that IQGAP1 binds to extracellular signal-regulated kinase (ERK) 2 and regulates growth-factor-stimulated ERK activity in breast cancer cells." (PMID 36499281, 2022). "miR-506, which is often downregulated in breast cancer, was reported to target the 3′UTR of IQGAP1 and impact cell proliferation, invasion, and adhesion, possibly through the RAS-MAPK pathway." (PMID 34439095, 2021). "IQGAP1 also binds directly to the HER2 receptor, which is overexpressed in 20–25% of breast cancers, and mediates its downstream signaling." (PMID 34439095, 2021). "Inhibiting IQGAP1 reduced anchorage-independent growth, migration, and invasion of MCF7 breast cancer cells in vitro, and tumor growth and vascularization of MCF7 xenografts in vivo." (PMID 34439095, 2021). "A recent study reported that IQGAP1, a scaffold protein of 189-kDa ubiquitously expressed in all human tissues, governs HER2 expression, phosphorylation and signaling in breast cancer cell lines." (PMID 26919099, 2016). "In breast cancer, other members of the HER-family are known to be involved in trastuzumab-resistance, as is overexpression of the scaffold protein IQGAP1." (PMID 26919099, 2016). "Moreover, in addition to the MAPK pathway IQGAP1 may modulate other oncogenic pathways by binding to E-cadherin and beta-catenin and by regulating the activation state of Rho A/Rho C to promote breast cancer cell proliferation and migration." (PMID 26033452, 2015). "Because the interaction between IQGAP1 and Cdc42 enhances cell proliferation and migration, we examined if small molecules NCGC00131308, NCGC00138812 and MLS000332963 can modulate these functions in breast cancer cells." (PMID 36253497, 2022). "A strong negative correlation between IQGAP2/phospho-ERK and a positive but non-significant correlation between IQGAP1/phospho-ERK were observed in breast cancer patients." (PMID 33846302, 2021). "Additionally, the interactions between IQGAP1 and the Raf/MEK/ERK cascade were found to be potential therapeutic targets for this subtype of breast cancer." (PMID 29262632, 2017).
breast carcinoma (continued). "IQGAP1 also localizes at cell–cell junctions in MCF-7 breast cancer cells and the increased junctional localization of this protein correlates with a reduction in E-cadherin localization at sites of cell–cell contact in breast cancer cells." (PMID 24352566, 2014). "have reported that a drop in IQGAP1 levels can shorten the formation of metastases without limiting primary or metastatic tumor growth in IQGAP1-knockdown and -knockout experiments conducted on human melanoma and breast cancer cells." (PMID 36276098, 2022). "Therefore, IQGAP1 level may be important both in the therapeutic response to CY-9d and in the Raf-MEK-ERK interactions in breast cancer cells." (PMID 29262632, 2017). "Unlike IQGAP1 and IQGAP3, which function as oncogenes in breast cancer, the role of IQGAP2 is still unexplored." (PMID 33846302, 2021). "A recent study in a systematic analysis found that in breast cancer cells endogenous IQGAP1 did not bind to any of the RAS members, but if IQGAP1 expression level is ectopically increased, it binds to RAS46." (PMID 33846302, 2021). "As corroboration, we observed a strong negative correlation between IQGAP1 and IQGAP2 in breast cancer tissues." (PMID 33846302, 2021). "In this study, we primarily reduced IQGAP1 expression in cell lines that were already highly proliferative and metastatic, and we did not see any reduction in primary tumor growth from LM2 breast cancer cells." (PMID 32051509, 2020). "This group found that miR-506 suppressed these functions and pathways by targeting IQGAP1, and the expression of IQGAP1 lacking the 3′UTR rescued the effects of miR-506 on breast cancer progression." (PMID 32353968, 2020). "IQGAP1 was specifically upregulated in truncated PALB2 breast IDC compared with the corresponding adjacent noncancerous tissue, similar to results reported for human breast cancer tissues and cell lines." (PMID 40868059, 2025). "Furthermore, diminished levels of IQGAP1 in MDA-MB-231 cells abrogated invasion and migration of breast cancer cells towards LPA, in the absence of serum, compared to cells expressing scrambled controls." (PMID 23405264, 2013). "Although direct interaction between Rac1 and WAVE2 is not detected in human breast cancer cells, Rac1 forms a complex with CLIP-170, a microtubule-binding protein, an actin cross-linking protein IQGAP1, and kinesin-1, one of the major motor proteins, under the growth-arrested conditions." (PMID 22315597, 2012).